PDGFRA (platelet derived growth factor receptor alpha)
Diseases named in the same sentence as PDGFRA in open-access papers (continued):
Sharing a sentence is not in itself a finding about the gene and the disease.
cancer (continued). "Molecularly, high sensitivity of mutant and cancer cells with the OPC feature toward IGF1R targeting likely stems from the intimate coupling between IGF1R and PDGFRα, as the coexpression of both RTKs largely occurs in OPCs in the brain." (PMID 33173731, 2020). "Among them, genes such as BCL2, CSNK2A1, EGFR, PDGFRA, VEGFA, etc., which have been proved to be targets of anti-cancer drugs, were proposed to provide general administrations for pan-cancers." (PMID 32523951, 2020). "In the cell cycle pathway, GSK3B, CDK2, and CDK1 are reduced by cisplatin in each cell line, and in cancer pathways, cisplatin reduces phosphorylation of GSK3B, AKT1, PDGFRa/b, PLCG1/2, and CDK2." (PMID 31929796, 2019). "Dozens of eIF4E2 mRNA targets have strong ties to cancer such as a group of receptor tyrosine kinases including EGFR, platelet-derived growth factor receptor-alpha, insulin-like growth factor 1 receptor, and HER-2, which most cancers overexpress at least one." (PMID 29317983, 2017). "With the aim of evaluating the effects of cancer cells upon the hASCs' capability of promoting angiogenesis, CD31, VEGF, PDGFA, PDGFRα, PDGFRβ gene expression was analysed at 7, 14 and 21 days." (PMID 28102844, 2017). "Several recent studies have similarly shown that Shp2 is required for TGF-β, EGF, or PDGFRα-driven EMT, in various types of cancers." (PMID 28208810, 2017). "The efficacy of ponatinib against multiple tyrosine kinases, such as ABL, PDGFRα, VEGFR2 and FGFR1 has been illustrated in several adult cancer types." (PMID 27564113, 2017). "Certainly, PDGFRα drives a remarkable change in cellular morphology, perhaps through the epithelial to mesenchymal transition (EMT) of cells, as a prerequisite to cancer cell dissociation, invasion, and metastasis." (PMID 27845909, 2016). "Second, our pipeline was able to recapitulate most known translocation events in cancer (ALK, BRAF, EGFR, FGFR1, 2 and 3, NTRK1, 2 and 3, PDGFRA, PRKCA, RAF1, RET, ROS1)." (PMID 25204415, 2014). "Two cancer genes including FHIT (collocated with FRA3B) and PDGFRA (collocated with FRA4B) that topped the concurrent LOH list in SNP array based analysis also show high levels of concurrent LOH in the sequencing based analysis." (PMID 24748104, 2014). "KIT/PDGFRA inhibitors such as imatinib mesylate are the mainstay of medical treatment for advanced GIST but they are not curative due in part to secondary mutations interfering with drug action or lack of dependence of cancer-initiating cells on KIT/PDGFRA signaling." (PMID 24116170, 2013). "In this study, we found that miR-34a and miR-34c target platelet-derived growth factor receptor alpha and beta (PDGFR-α and PDGFR-β), cell surface tyrosine kinase receptors that induce proliferation, migration and invasion in cancer." (PMID 23805317, 2013). "The 2Chr7:1n,1d cells exhibited a more invasive phenotype by expressing higher levels of the pro-invasive genes (IGFBP2, PDGFRA, RHOC, FOXM1, and PLAU) and matrix metalloproteinase 2 (MMP2), all of which are well-reported for cancers, including GBM." (PMID 24282558, 2013). "Blood samples for CTC analysis were obtained from 24 cancer patients in a multi-center all-comer Phase I study of MEDI-575, a novel anti-PDGFRα antibody." (PMID 23990866, 2013). "More surprisingly, 26 of the 29 known Hsp90 client kinases that we also quantified in the reference Hs68 cell line showed significantly reduced levels after 24 h of treatment, including well known cancer-relevant proteins like EGFR, Met and PDGFRα/β." (PMID 22277058, 2012). "In this study, we investigated the occurrence of primary cilia in human wt and cancer OSE cells with a focus on the correlation between AURA and the presence or absence of primary cilia with functional Hh signaling and expression of PDGFRα." (PMID 23351307, 2012).
cancer (continued). "Moreover, CAF-derived PDGFC can facilitate the EMT of cancer cells and increase matrix metalloproteinase 2 (MMP2) expression through the PDGFRA-mitogen-activated protein kinase/extracellular signal-regulated kinase (MAPK/ERK) pathway." (PMID 40501228, 2025). "Among the subsets, the PDGFRA+ subset expanded in metaplasia and cancer compared with normal tissue." (PMID 40075643, 2025). "Ten tumors were negative for mutations in KIT, PDGFRA, and RAS-pathway genes (BRAF, RAS isoforms, and NF1), and for all other 161 cancer-relevant genes that were included in our NGS panel." (PMID 39199677, 2024). "Unlike small molecules for PDGFR, which do not discriminate PDGFR from normal versus cancer cells, these antibodies do not recognize PDGFRA in the benign cells and thus have no impact on benign tissues." (PMID 39082961, 2024). "Increased expression of STRN was found in different cancers, which induced cell cycle progression and invasiveness by activating downstream transcription factors, including misshapen-like kinase 1, RhoA, TRAF2, NCK-interacting protein kinase and PDGFRA." (PMID 38215077, 2024). "In this sense, the platelet-derived growth factor receptor alpha (PDGFRA) gene is directly targeted by miR-34a in this cancer type, thus constituting a negative feedback regulatory loop that results in GB progression." (PMID 38473710, 2024). "The PDGFRα+ subset expanded in metaplasia and cancer compared with normal, maintaining a close proximity with the epithelial compartment." (PMID 37196797, 2023). "Oncogenes including EGFR, PDGFRA, ERBB2, and Proto-Oncogene tyrosine-protein kinase (KIT) are found on ecDNA in glioblastoma and are amplified in huge numbers that have a key role in cancer promotion, according to research." (PMID 35614494, 2022). "However, the expression of the PDGFRA, PDGFRB, CDH11, and EMILIN1 genes was mainly reduced in fibroblasts after co-cultivation with cancer cells." (PMID 36263012, 2022). "This suggests a significant function of PDGFRA and PDGFRB in S:E fusion-positive cancer." (PMID 36579559, 2022). "KIT and PDGFRA play a major role in the oncogenic process in gastrointestinal stroma tumors (GIST) and small molecules have been employed with great success to target the KIT and PDGFRA pathways in this cancer." (PMID 35965531, 2022). "OS was significantly shorter in patients with the CN gain of PDGFRA pathway for all six cancer types compared with the No CN gain group (P < 0.05)." (PMID 35212838, 2022). "Compared with other mesenchymal stem cells, the most highly expressed oncogene and tumor suppressor genes in WJ-MSCs are PDGFRA and TGFBR2, which may be related to their strong anti-cancer properties." (PMID 36011369, 2022). "For instance, lncRNA AK023391 exerts its cancer-promoting effect by activating the PI3K/Akt signaling pathway; SNHG8 enhances the proliferation and invasion of GC cells by targeting the miR-491/PDGFRA axis." (PMID 34037089, 2021). "Affinity extraction demonstrated that rSLURP-1 in A549 cells forms a complex not only with α7-nAChR, but also with PDGFRα and epidermal growth factor receptor (EGFR), which are known to be involved in regulation of cancer cell growth and migration and are able to form a heterodimer." (PMID 34595181, 2021). "For GI cancer, EGFR, PDGFRA, VEGFA, PDPK1, and MCL1, etc. could be validated as drug targets for anti-cancer drugs." (PMID 32523951, 2020). "CA-MSCs did not appear to be cancer-associated fibroblasts (CAFs) as demonstrated by the absence of upregulation of α-SMA, FAP, FSP1, or PDGFRα." (PMID 31504643, 2020).
cancer (continued). "Murine PDGFRα increased particularly in xenografts derived from HT29 and MCF7 cells (HT29 26.02 ± 2.18% versus RH30 3.0 ± 1.43%), suggesting that epithelial cancer cells require much more CAFs to grow." (PMID 33585217, 2020). "Consistently, Ki67 expression by IHC in cancer cells (ratio of Ki67‐positive/total nuclei in PDGFRα‐negative cells) was increased in mini‐organotypic co‐cultures with other pCAF subtypes (p = 0.001)." (PMID 30575030, 2019). "Higher levels of phosphorylated PDGFRα/β and EMT proteins were detected in spheroid cultures (enriched for cancer stem cells), while the PDGFRα/β-targeting tyrosine kinase inhibitor imatinib reduced migration and invasion up to 80% and reduced expression of EMT proteins." (PMID 31418125, 2019). "On the contrary, EPHB2, ERBB4, FGFR1, PDGFRA, KDR, and FLT1 genes showed deletion in cancer cells." (PMID 32038722, 2019). "PDGFRA is connected to AKT3 activity and regulations in participates in cancer related mechanisms." (PMID 29321820, 2017). "Yet, in another group, only receptors were significantly increased (e.g., PDGFRA and CCR8) suggesting that corresponding ligands, PDGF and CCL1, often overexpressed in cancers, may create a chemokine gradient facilitating recruitment of M-LECP." (PMID 28598999, 2017). "Our data indicate that it may be beneficial to assess PDGFRα and FGFR1 levels to determine if ponatinib has similar efficacy in these cancers." (PMID 27783942, 2016). "MEDI-575 is a human mAb that selectively binds to PDGFRα with high affinity, inhibiting signaling from PDGFRα on cancer cells and supportive stroma without inhibiting PDGFRβ." (PMID 25149088, 2014). "Our results revealed that the expression of PDGFRα and EpCAM was mutually exclusive in all cancer cell lines tested (data not shown)." (PMID 23990866, 2013). "In contrast, the fraction of growth-arrested cancer OSE cells with primary cilia was less than 20%, and these cells displayed aberrant Hh signaling and down-regulated expression and/or glycosylation of PDGFRα." (PMID 23351307, 2012). "Indeed, we here show that PDGFRα and essential components of the Hh pathway, including SMO, PTCH1 and GLI2, localize to primary cilia of wt OSE cells and that cancer OSE cells display increased basal expression of Hh responsive genes." (PMID 23351307, 2012). "The paralog of PDGFRA, PDGFRB, has two alternative promoters and is also a cancer driver gene." (PMID 20208995, 2010). "In addition, compared with the low-risk group, focal amplification peaks were observed for well-characterized cancer-related genes HAS2 (8q24.13) and PDGFRA (4q12), which might be the reason for the poor outcomes in the high-risk group." (PMID 37663248, 2023). "However, characterization and clinical properties of PDGFRA CN gain in whole cancers have not been well documented." (PMID 35212838, 2022). "As the FGF2 rs1048201, PDGFRB rs246395, PDGFRA rs2228230, MMP2 rs243865, rs7201, and TIMP2 rs7501477 have not been previously examined in HNSCC in terms of survival and treatment outcome, this is most likely the first report describing their prognostic and predictive value in this type of cancer." (PMID 35406617, 2022). "As in our study, the RNA-seq results showed that PDGFRA was down-regulated, TGFBR2 was up-regulated, and the expression of related apoptosis markers was increased after NR2F2 knockdown, suggesting that NR2F2 promotes the effect of WJ-MSCs in inhibiting cancer cell proliferation." (PMID 36011369, 2022). "Strong expression-driven dependency was found for PDGFRA in cancer cells of the central nervous system (Pearson’s correlation coefficient [R] = −0.53, FDR = 3.5E − 3) and stomach (R = −0.8, FDR = 1E − 3) lineages, whereas PDGFRA was overexpressed in ~18% of cases in MB and STAD." (PMID 34552204, 2021). "Thus, PDGFRα is a downstream target of CREB at least in MEFs and cancer cells." (PMID 33568640, 2021).
cancer (continued). "ISLR/Meflin is a newly discovered surface and secreted pluripotency-related protein whose over-expression has been described in cancer stroma and fibrotic diseases, and a recent immunoprecipitation study has demonstrated its interaction with receptor tyrosine kinases (RTKs) such as EGFR and PDGFRA." (PMID 28415643, 2017). "We speculate that the inhibition of PDGFRα by DHA is important for its actions on not only cell growth, proliferation and migration, but also apoptosis and angiogenesis, which would facilitate the rational design of effective DHA-based cancer therapy." (PMID 29387451, 2017). "Therefore, Endocan may serve as an additional PDGFR ligand allowing cancer cells to activate PDGFRA signaling pathway, even if PDGFs are absent or diminished." (PMID 39773984, 2025). "Furthermore, cancer-derived fibroblasts showed a 2-fold higher number of PDGFRα+ fibroblasts compared with metaplasia-derived fibroblasts, and intra- or extracellular FBLN2 positivity was slightly up-regulated in metaplasia-derived fibroblasts compared with cancer-derived fibroblasts." (PMID 37196797, 2023). "Finally, the effect of the recent development of KIT/PDGFRA inhibitors is ripretinib (formerly DCC-2618), whose effectiveness in inhibition of a wide range of KIT mutants in patients with drug-resistant GISTs has been confirmed in preclinical cancer models and preliminary clinical data." (PMID 36291774, 2022). "Similarly to KIT, PDGFRA and their ligands, insulin-like growth factor (IGF)-1 receptor (IGF1R), a type 2 RTK, and its ligands IGF1 and IGF2 play critical roles in normal growth and development, as well as in cellular stress, aging and cancer by stimulating protein synthesis and the cell cycle." (PMID 24116170, 2013). "In our scRNA-seq, PDGFRB was most dominantly expressed in F-pericytes, unlike PDGFRA, while PDGFC was weakly expressed in CAFs and myeloid cells, but not in cancer cells." (PMID 40075643, 2025). "For the cancer types that performed the worst, liver hepatocellular carcinoma included none of the used oncogenes (AR, KLF4, PDGFRA, and RET) or tumor suppressors (BRCA2, CDKN2A, and TSC1) that were linked to it." (PMID 31900418, 2020). "Nearly 80% or more of SNVs in FLT3, PDGFRA, PGR, and RET were not expressed among all cancer patients." (PMID 29721196, 2018). "Of note, plasma membrane NOTCH1 was uniquely associated with the ablumenal aspect of the endothelium, in direct contact with closely adherent perivascular cells that expressed the HIF-induced non-canonical NOTCH antagonist DLK1, a cancer pericyte-related antigen, together with SMA and PDGFRA." (PMID 29305721, 2018). "Further, in cancer OSE cells, there is a defect in expression and/or glycosylation of PDGFRα, in that SK-OV3 cells are not up-regulating PDGFRα expression during growth arrest, and that both up-regulation and glycosylation of the receptor is hampered in OVCAR3 cells." (PMID 23351307, 2012).
infection (51 papers, 2012 to 2025). The state of being infected such as from the introduction of a foreign agent such as serum, vaccine, antigenic substance or organism. "Mechanistically, Stat1-deficiency promotes lytic infection but abolishes latent persistence of murine cytomegalovirus in PDGFRα-positive fibroblastic cells in vivo." (PMID 37248241, 2023). "The gHgLgO complex uses PDGFRα as an entry receptor, an interaction which is resolved on a structural basis and also on the level of its role in infection." (PMID 40705828, 2025). "For infection of fibroblasts and neuronal cells, the virus targets platelet-derived growth factor receptor alpha (PDGFRα) and uses its glycoprotein complexes gH/gL/gO for entry." (PMID 41194660, 2025). "Studies with HCMV lacking gO had indicated that gHgLgO, independently of binding to its cellular receptor PDGFRα, plays an important second role in infection." (PMID 40705828, 2025). "The entry receptors for HCMV are platelet-derived growth factor receptor-α (PDGFRα), which mediates the infection of fibroblasts, and neuropilin-2 (Nrp2), which is essential for endothelial and epithelial cell infection." (PMID 39134803, 2024). "A more recent study showed that the major site of latency depends on the viral route of infection: PDGFRα+ fibroblastic cells are the major site following i.n. infection, and endothelial cells are the major site following i.p. infection." (PMID 39134803, 2024). "Since antibodies to TC appear later than antibodies to PC and infection of HELF is mainly dependent on TC interaction with PDGFRα, NAb are detected only late in HELF." (PMID 36901847, 2023). "Following the infection of Pdgfra-CreERT2 (+/−) mice with MCMVfloxSTOP-GFP it is expected that the viruses that replicate in PDGFRα+ FC become genetically recombined so their progeny gives rise to GFP+ plaques on monolayers of MEFs." (PMID 37248241, 2023). "In sum, the profile of viral gene expression in PDGFRα+ FC from latently infected mice is at odds with persistent lytic infection." (PMID 37248241, 2023). "At 12 h post infection, splenic PDGFRα+ FC expressed high levels of all three viral transcripts at levels at least 1000-fold higher than in any tested subset of PDGFRα+ FC from latently infected mice." (PMID 37248241, 2023). "To address this in vivo, we first investigated if lytic gene expression was induced in PDGFRα+ FC during the acute phase of infection with MCMV." (PMID 37248241, 2023). "The trimer binds its cellular receptor PDGFRα on fibroblasts and also appears to be required for infection of other cell types." (PMID 35891541, 2022). "PDGFRα-Fc inhibits cell-free infection of HCMV by acting as a decoy receptor that binds to the viral envelope protein gO, whereas its effect on cell-associated spread has not been conclusively elucidated." (PMID 34578361, 2021). "While differences in the efficiency of neutralization of strains VHL/E, AD169, Towne and Merlin were observed for the PDGFRα-Fc mutant, infection of all strains was completely inhibited at 1000 ng/ml." (PMID 33780515, 2021). "With a half-maximal effective concentration (EC50) of 10 ng/ml in fibroblasts, inhibition of fibroblast infection by PDGFRα-Fc is highly efficient as compared to neutralization by monoclonal antibodies." (PMID 33780515, 2021). "With regard to cell-free infection however, PDGFRα-Fc has several features that make it a promising alternative to monoclonal antibodies for prevention of HCMV transmission and disease." (PMID 33780515, 2021). "These disparate infection rates correlated with expression of PDGFRA, which facilitates HCMV uptake." (PMID 34575976, 2021). "Similar to antibodies, PDGFRα-Fc binds to the virus and blocks infection, but it is more potent and has a broader activity of inhibition which makes it a promising alternative." (PMID 33780515, 2021).